TENM4 (teneurin transmembrane protein 4)
Description:
Involved in neural development, regulating the establishment of proper connectivity within the nervous system. Plays a role in the establishment of the anterior-posterior axis during gastrulation. Regulates the differentiation and cellular process formation of oligodendrocytes and myelination of small-diameter axons in the central nervous system (CNS). Promotes activation of focal adhesion kinase. May function as a cellular signal transducer (By similarity).
Synonyms: Ten-4; Ten-m4; KIAA1302; ODZ4; TNM4; TEN4; DOC4; ETM5
Tractability: Antibody: UniProt places it where antibodies can reach, with high confidence; its Gene Ontology location is reachable by antibodies, with high confidence; UniProt predicts a signal peptide or a membrane-spanning region. PROTAC: ubiquitination databases record sites on it; its protein half-life has been measured.
Gene: Protein-coding gene on chromosome 11 (78,652,829 to 79,441,030, reverse strand). Ensembl gene ENSG00000149256.
Subcellular location: Cell membrane; Cell projection; Nucleus; Cytoplasm
Gene Ontology:
Molecular function: protein binding; protein homodimerization activity; signaling receptor binding; identical protein binding
Biological process: central nervous system myelin formation; neuron development; regulation of myelination; axon guidance; positive regulation of gastrulation; positive regulation of myelination; positive regulation of oligodendrocyte differentiation; synaptic membrane adhesion; signal transduction
Cellular component: plasma membrane; cytoplasm; glutamatergic synapse; neuron projection; nucleus; membrane
Genetic constraint (gnomAD): Loss-of-function variants: 81 observed, 234.24 expected, observed/expected ratio (o/e) 0.35, 90% interval 0.29 to 0.42. The upper end of that interval is the gene's LOEUF score, 0.42, which puts it in group 1 of 6, group 1 being the genes least tolerant of losing a copy. Missense variants: 3,124 observed, 3,716 expected, observed/expected ratio (o/e) 0.84, 90% interval 0.81 to 0.87. Synonymous variants: 1,409 observed, 1,476.5 expected, observed/expected ratio (o/e) 0.95, 90% interval 0.91 to 1.
Homologues: Orthologues: chimpanzee TENM4 (99% identical), macaque TENM4 (99% identical), rat Tenm4 (97% identical), guinea pig TENM4 (97% identical), mouse Tenm4 (96% identical), pig TENM4 (95% identical), rabbit TENM4 (95% identical), tropical clawed frog tenm4 (87% identical), zebrafish tenm4 (79% identical), Drosophila melanogaster Ten-m (32% identical), Drosophila melanogaster Ten-a (32% identical), Caenorhabditis elegans irg-7 (15% identical), and 1 more. Paralogues in human: TENM3 (67% identical), TENM2 (63% identical), TENM1 (63% identical), NAGPA (5% identical).
Diseases named in the same sentence as TENM4 in open-access papers:
TENM4 is named in the same sentence as 63 diseases in open-access papers, as found by Europe PMC text mining. Sharing a sentence is not in itself a finding about the gene and the disease. The quoted sentences say what the papers report.
bipolar disorder (13 papers, 2013 to 2023). A disorder of the brain that causes unusual shifts in mood, energy, activity levels and the ability to carry out day-to-day tasks. "In line with its involvement in the nervous system, TENM4 has also been implicated in several mental disorders such as bipolar disorder, schizophrenia, and autism." (PMID 35011736, 2022). "A TENM4 risk variant has also been associated with mood disorders, and with the early onset of bipolar disorders." (PMID 33652578, 2021). "Recently, a large-scale genome-wide association study (GWAS) identified an intronic variant in TENM4 (ODZ4) as being associated with bipolar disorder, a severe mood disorder that affects over 1% of the population." (PMID 23521771, 2013). "In line with the important role of TENM4 in central nervous system development, ODZ4 has been identified as a risk gene for many types of mental diseases, including bipolar disorder (Psychiatric GWAS Consortium Bipolar Disorder Working Group, 2011), schizophrenia, and autism." (PMID 35011736, 2022). "Indeed, genome-wide association studies have identified TENM4′s involvement in bipolar disorder susceptibly, and its role as a risk gene for schizophrenia." (PMID 33652578, 2021). "In addition, TENM4 is associated with bipolar disorder in a recent genome-wide association study with a large sample size." (PMID 30745909, 2018). "TENM4 rare variants are also found to be associated with bipolar disorder." (PMID 30745909, 2018). "Moreover, a recent study has reported that rare variants in TENM4 might contribute to etiology of bipolar disorder." (PMID 30745909, 2018).
schizophrenia (12 papers, 2018 to 2024). A major psychotic disorder characterized by abnormalities in the perception or expression of reality. "Migrating neurons, corticothalamic projection neurons (CThPNs) and callosal projection neurons (CPNs) showed increased expression of Tenm4, a risk gene for schizophrenia that encodes a transmembrane protein that regulates axon guidance." (PMID 38775708, 2024). "Nevertheless, we found a number of genes in this list that have a reported association to schizophrenia or other neuropsychiatric disorders, for example, TENM4, NXN, NRXN1, GALNT5, SHANK3 and RELN." (PMID 36711134, 2022). "Recently, a missense mutation of the gene has been found to co-segregate with schizophrenia, suggesting that TENM4 has a potential role in this pathology." (PMID 33652578, 2021). "In the current study, by using exome sequencing, we demonstrated cosegregation of a novel missense mutation in TENM4 with schizophrenia in a Chinese family." (PMID 30745909, 2018). "In an epigenetic study, the Tenm4 gene has recently been implicated in a rodent model of schizophrenia." (PMID 30745909, 2018). "With additional rare TENM4 mutations significantly associated with schizophrenia, our findings suggested that TENM4 were a candidate gene for the disease in the SCZD2 locus at 11q14-21." (PMID 30745909, 2018). "In the current study, a rare missense mutation (c.6724C>T; p.R2242C) in TENM4 showed cosegregation with schizophrenia in a three-generation family." (PMID 30745909, 2018). "The study thus demonstrated increased TENM4 mutation burden in schizophrenia and suggested that TENM4 could probably be a candidate gene for schizophrenia in the SCZD2 locus." (PMID 30745909, 2018). "TENM4 is located within a region that was previously linked to schizophrenia (SCZD2, OMIM %603342)." (PMID 30745909, 2018). "Therefore, our data suggested association of TENM4 with schizophrenia, while its association with cognitive impairment needs to be investigated in further study." (PMID 30745909, 2018). "The mutations detected in schizophrenia patients in the current study were located within a YD repeat containing region in the extracellular domain of TENM4 protein, which was essential for extracellular protein–protein interaction and signal transduction for transmembrane proteins." (PMID 30745909, 2018). "Furthermore, a role of Tenm4 has been implicated in a rodent model of schizophrenia." (PMID 30745909, 2018). "In addition, two more rare mutations were identified in unrelated sporadic schizophrenic patients, suggesting the exon surrounding p.R2242C in TENM4 could be a potential mutation hotspot for schizophrenia." (PMID 30745909, 2018). "In line with the important role of TENM4 in central nervous system development, our findings suggested that increased rare variants in TENM4 could be associated with schizophrenia, and thus TENM4 could be a novel candidate gene for schizophrenia in the SCZD2 locus." (PMID 30745909, 2018). "Others participate in neurodegenerative conditions; PD, schizophrenia, and intellectual disability (Tenm4, Pde4dip, Grid2, Arhgap18)." (PMID 36902345, 2023). "A recent study identifies TENM4 as a novel candidate gene for a Han Chinese family with schizophrenia." (PMID 33154736, 2020). "In the current study, by using exome sequencing we identified a novel rare mutation in the teneurin transmembrane protein 4 gene (TENM4, also named ODZ4), which cosegregated with schizophrenia in a Han Chinese family." (PMID 30745909, 2018). "In the current study, we conducted exome sequencing in a three-generation family affected by schizophrenia, and identified a novel candidate gene TENM4 in a linkage locus SCZD2 at 11q14-21." (PMID 30745909, 2018). "TENM4 is known to play an important role in central nervous system development and could be a candidate gene for schizophrenia." (PMID 36310845, 2022).
schizophrenia (continued). "By showing co-segregation with schizophrenia in the family, our findings thus suggested that TENM4 could be a candidate gene in the SCZD2 locus." (PMID 30745909, 2018). "Although TENM4 has not been clinically linked to schizophrenia previously, recent studies have already implicated its possible role in mental illness and cognition." (PMID 30745909, 2018). "Similarly, neurons from schizophrenia patients differentiated in vitro showed misexpression of various genes including TENM4, NRG1 and ERBB4, suggestive of a functional connection between these proteins." (PMID 30618566, 2018). "The association between TENM4 mutations with schizophrenia in the current study was not contradictory to previous literature regarding architecture of schizophrenia genetic risk." (PMID 30745909, 2018). "We herein performed exome sequencing in a Han Chinese schizophrenia family and identified a missense mutation (c.6724C>T, p.R2242C) in the teneurin transmembrane protein 4 (TENM4) gene in the SCZD2 locus, a region previously linked to schizophrenia at 11q14-21." (PMID 30745909, 2018). "Among the three TENM4 mutations found in schizophrenia patients, p.D2294N was found in a heterozygous individual (MAF = 8.3 × 10−6) in the ExAC database indicated that these deleterious TENM4 mutations might exist in the general population, yet with an extremely low frequency." (PMID 30745909, 2018). "The rare deleterious TENM4 variants found in schizophrenia patients might not affect cognition directly." (PMID 30745909, 2018).
essential tremor (9 papers, 2017 to 2025). A relatively common disorder characterized by a fairly specific pattern of tremors which are most prominent in the upper extremities and neck, inducing titubations of the head. "Several cases reported the nucleotide variant of TENM4 was a risk factor for essential tremor from the early-onset PD patients, which highlight the genetic overlap between PD and tremor." (PMID 41327336, 2025). "Loss-of-function and missense variants in TENM4 are associated with early onset PD and essential tremor, a potential risk factor for developing PD51–60." (PMID 36774388, 2023). "Mutations of TENM4 in humans were manifested as an essential tremor, which is a common movement disorder." (PMID 33133146, 2020). "Some missense mutations of TENM4 are confirmed to cause essential tremor in Caucasian populations; however, the relationship between TENM4 and essential tremor in the Han Chinese population still needs further clarification." (PMID 33154736, 2020). "Some years later, 12 novel missense variants in TENM4 were discovered in Spanish patients affected with essential tremor, a phenotype also observed in mice upon Teneurin-4 knock-out." (PMID 30618566, 2018). "These include a null mutation of TENM3 in microphtalmia and missense mutations of TENM4 in essential tremor." (PMID 28472127, 2017). "Mutations in the teneurin transmembrane protein 4 (TENM4) gene, known to be involved in neuropsychiatric disorders, have been identified in three pedigree of essential tremor (ET) from Spain." (PMID 33414808, 2020). "Linkage studies conducted in families with ET have reported mutations in ETM2 (essential tremor monogenetic locus 2) and (fused in sarcoma) FUS, while other studies have linked (leucine-rich repeat and Ig domain containing 1) LINGO1, FUS and teneurin transmembrane protein 4 (TENM4) with ET3." (PMID 29593234, 2018). "In contrast, TENM4 variants could not be associated with essential tremor in Canadian patients." (PMID 30618566, 2018).
breast carcinoma (7 papers, 2017 to 2022). "Most of the TENM4 mutations that are observed in tumors occur in breast cancer, in which TENM4 plays a role in cells’ migration and stemness." (PMID 35011736, 2022). "By investigating publicly available breast cancer patient databases, we found that TENM4 mRNA expression increases in both ductal and lobular invasive carcinomas compared to healthy breast tissue, and higher expression of TENM4 mRNA in TNBC patients is associated with a poorer RFS." (PMID 33672732, 2021). "A deep knowledge of the role of both the TENM4 protein and miR-708 in breast cancer cells and tumors will facilitate the investigation of combinatorial strategies that aim to halt tumor progression and prolong cancer patient survival." (PMID 35011736, 2022). "Moving beyond gene alterations, an in silico analysis, performed using several publicly available datasets, showed that there is a trend of increased TENM4 mRNA expression in breast cancer as compared to normal tissues." (PMID 35011736, 2022). "Herein, we review the currently available data for the role of TENM4 in breast cancer and propose it as a potential biomarker and novel target." (PMID 35011736, 2022). "Herein, we review the currently available data for TENM4′s role in breast cancer and propose its use as both a novel target with which to ameliorate patient prognosis and as a potential biomarker." (PMID 35011736, 2022). "The NRG1 fusion transcript of breast cancer cell line MDA-MB-175 was originally described as a fusion of DOC4 (now TENM4, encoding teneurin transmembrane protein 4, also called ODZ4) to NRG1." (PMID 33413557, 2021). "The expression of the fusion protein is controlled by the TENM4 promoter, and it has been shown to induce breast cancer cell proliferation through the constitutive activation of the ErbB3–ErbB2 complex via Υ-heregulin-dependent autocrine stimulation." (PMID 33652578, 2021). "Meta-analysis of breast cancer datasets shows that TENM4 mRNA is up-regulated in invasive carcinoma specimens compared to normal breast and that high expression of TENM4 correlates with a shorter relapse-free survival in TNBC patients." (PMID 33672732, 2021). "TENM4 silencing in mammary cancer cells significantly impaired tumorsphere-forming ability, migratory capacity and Focal Adhesion Kinase (FAK) phosphorylation." (PMID 33672732, 2021). "All these data suggest that, in different breast cancer subtypes, TENM4 plays a role in, tumorsphere formation, and self-renewal, and that it contributes to the malignant phenotype of breast cancer cells, likely by promoting metastatic progression and possibly drug resistance." (PMID 35011736, 2022). "However, the functional role that TENM4 plays in breast cancer still needs to be better evaluated, and further studies are required to better understand the involvement of TENM4 in breast cancer progression." (PMID 35011736, 2022). "Moreover, as miR-708 is spliced out from TENM4 mRNA, we also report data on the tumorigenic role of miR-708 deregulation in different breast cancer subtypes." (PMID 35011736, 2022). "Taken together these findings suggest that circulating TENM4 could be a potential disease biomarker for breast cancer that deserves further investigation." (PMID 33672732, 2021). "Considering that a high percentage of both ductal and lobular invasive carcinomas of the breast are estrogen receptor positive, TENM4 could be a relevant target not only in TNBC but also in other breast cancer subtypes." (PMID 33672732, 2021). "Moreover, a potential role for TENM4 in breast cancer stem cell self-renewal has been suggested by the recent identification of TENM4 up-regulation in human TNBC stem cell-enriched mammary tumorspheres, compared to parental ones." (PMID 33652578, 2021). "Indeed, TENM4 mRNA and protein expression has been found in several human breast cancer cell lines and in breast tumor samples." (PMID 33652578, 2021).
breast carcinoma (continued). "Moreover, the analysis of the plasma from a little cohort of breast cancer patients and healthy donors revealed that TENM4 protein can be detected and is more abundant in patients as compared to healthy donors." (PMID 33672732, 2021). "However, very few data are available on the functional role of TENM4 in breast cancer." (PMID 35011736, 2022). "Breast cancer is another tumor type in which TENM4 may have a contribution." (PMID 33652578, 2021). "The possible involvement of TENM4 overexpression in breast cancer aggressiveness has also been suggested by its correlation with a worse RFS and OS in grade 3 breast cancer patients." (PMID 35011736, 2022). "Subsequently, we demonstrated that TENM4 expression is not limited to TNBC cells, but that it is also found in cells from other breast cancer subtypes." (PMID 35011736, 2022). "Moreover, the significant increase in the TENM4 mRNA level observed in colorectal tumors, compared to normal colon tissue in a mouse model of colorectal cancer may suggests that TENM4 may become an interesting and suitable target, not only for breast cancer, but also for other tumor histotypes." (PMID 35011736, 2022). "Preliminary results from the small cohort of 48 breast cancer patients, including 7 TNBC patients, showed significantly higher amount of TENM4 in the plasma of tumor-bearing patients as compared to healthy donors." (PMID 33672732, 2021). "For this analysis, we included also other human breast cancer cell lines, such as MDA-MB-231 (TNBC), MCF7 (ER+/Her2−) and SK-BR-3 (ER−/Her2+) cells, demonstrating the up-regulation of TENM4 also in the tumorspheres derived from these cell lines." (PMID 33672732, 2021). "In this context, one of the first traceable publications described a chromosomal translocation involving the TENM4 and NRG1 (Neuregulin-1) genes in a breast cancer cell line." (PMID 30618566, 2018). "We have therefore demonstrated the potential relevance of 4T1, TUBO, and BALB-neuT tumors as appealing models with which to study the involvement of TENM4 in TNBC- and HER2-positive breast cancer’s initiation and progression, and the clinical impact of its immune-targeting." (PMID 35011736, 2022). "Interestingly, in the breast cancer cell line MDA-MB-175, TENM4 is involved in a translocation that generates the TENM4–neureguilin-1 fusion gene, resulting in Υ-heregulin fusion protein production." (PMID 33652578, 2021). "However, to the best of our knowledge, the involvement of TENM4 in chemotherapy resistance in breast cancer has not yet been thoroughly investigated." (PMID 35011736, 2022). "Interestingly, TENM4 overexpression has been detected in CSC-enriched tumorspheres that were derived from murine and human breast cancer cell lines, including 4T1 (murine TNBC), HCC-1806 (human TNBC), MDA-MB-231 (human TNBC), MCF-7 (human ER-positive) and SK-BR-3 (human HER2-positive)." (PMID 35011736, 2022). "Despite their limited relevance for immunological studies, the use of xenografts with human breast cancer cells, such as MDA-MB-231, for translational purpose may be of paramount importance for gaining insight into the role of TENM4 in the biology, progression, and metastatization of human TNBC." (PMID 35011736, 2022). "While no data are currently available on TENM4 expression and role in normal breast tissues, the first potential link between breast cancer and ODZ4 was detected in the human breast cancer cell line MDA-MB-175." (PMID 35011736, 2022).